IL17A (interleukin 17A)
Diseases named in the same sentence as IL17A in open-access papers (continued):
Sharing a sentence is not in itself a finding about the gene and the disease.
mastitis (continued). "By using mouse mastitis models, we and others showed that IL-17A is involved in the innate immune response of the MG to S. aureus infection." (PMID 27100324, 2016). "So far, production of IL-17A in an infected udder was only reported in clinical mastitis after experimental Streptococcus uberis infection." (PMID 26062913, 2015). "Results indicated that IL-17A increased the response of PS cells when they were stimulated with either E. coli strain 1303 or E. coli P4, a prototypical mastitis isolate." (PMID 26062913, 2015). "All these cell types are known to be recruited during mastitis in the bovine MG, but it remains to document which leukocytes are able to produce IL-17A in the bovine species." (PMID 23696826, 2013). "We have shown that Ccl20 is expressed by bovine MEC in response to IL-17A and IL-17F, and Ccl20 has been shown by several groups to be a major response gene of bovine MEC exposed to MAMPs or mastitis-associated bacteria." (PMID 23696826, 2013). "In summary, this study shows that IL-17A could be used as an important indicator for assessing the bacterial infections of mammary glands, indicating that IL-17A could be regarded as one potential therapeutic target for mastitis." (PMID 38891619, 2024). "The production of the signature cytokines IL-17A, IL-17F, and IL-22 in milk over the course of S. uberis, E. coli, and S. aureus mastitis suggest that innate type 3 immunity is part of the natural immunity to mastitis." (PMID 35214754, 2022). "In induced bovine mastitis, IL-17A mediates host defense-pathogen interactions during mastitis." (PMID 35335696, 2022). "The results infer that IL-17A and IL-17F genes could be crucial modifiers of inflammatory diseases and the SNPs might be useful markers of genetic resistance against bovine mastitis development in both dairy and dual purpose cattle." (PMID 28101335, 2017). "The results indicate that IL-17F and IL-17A could be powerful candidate genes of mastitis resistance and the significant SNPs might be useful genetic markers against mastitis in both dairy and dual purpose cattle." (PMID 28101335, 2017). "Production of IL-17A during S. uberis mastitis was recently demonstrated." (PMID 26062913, 2015). "Together with data from the literature, these results support the hypothesis that IL-17A and IL-17 F could play an important role in mediating of host-pathogen interactions during mastitis." (PMID 26062913, 2015). "However, the specific function and mechanism of the IL-17A immune axis in LPS-induced cow mastitis remain unclear, and its function in the defense against mastitis needs to be further investigated." (PMID 38891619, 2024). "Moreover, Roussel and his co-workers experimentally proved that IL-17 F and IL-17A could play an essential role in regulating host-pathogen relations during mastitis development." (PMID 36911690, 2023). "Furthermore, the polymorphism (1578A>G) in IL17A regulated the milk SCC and, thus, their expression might be a potential marker for mastitis susceptibility." (PMID 36911690, 2023). "Certainly, the expression of the IL-17A gene is induced in udder tissues of cows experimentally infected with E. coli, suggesting IL-17A could play an important role in mediating host-pathogen interactions during mastitis." (PMID 35335696, 2022). "It is reported that the IL-17A genes show a substantial correlation with mastitis indicator traits in Holstein cows, suggesting that they could be used as essential genetic markers in a mastitis sensitivity investigation in dairy animals." (PMID 36134995, 2022). "The detection of IL-17A in multiple hosts and in response to different pathogen species confirms its importance in the context of mastitis and suggests that its induction through innate and or adaptive immune stimulation may be important in protecting against IMI." (PMID 34179160, 2021). "Moreover, mouse mastitis models have shown a positive effect of IL-17A on the course of mastitis." (PMID 33059767, 2020).
mastitis (continued). "We have recently shown that bovine MEC respond to bovine IL-17A by producing chemokines and overexpressing a number of genes related to innate immune defenses, and up-regulation of the gene coding IL-17A in milk leukocytes from cows suffering from S. aureus mastitis has been reported." (PMID 23758654, 2013). "In summary, in clinical mastitis-affected cows, immunoreactive cell mean counts in milk increased for IL-4, IL-6, IL-12, and IL-17A and remained nearly absent for IL-13." (PMID 35335696, 2022). "The udder has therefore the ability to secrete IL-17A but its contribution to the defence against E. coli mastitis has not been investigated." (PMID 26062913, 2015). "Together, data about naturally occurring subclinical and clinical mastitis demonstrate inflammatory responses to intramammary infection driven by IL-1α, IL-4, IL-12, IL-17A, and IFN-γ in subclinical mastitis, and IL-1α, IL-4, IL-6, and IL-17A in clinical mastitis." (PMID 35335696, 2022).
pulmonary TB (42 papers, 2010 to 2026). "The Th17 response has been associated as a correlate of protection in pulmonary TB and is characteristically represented by the cytokine IL-17A." (PMID 33679685, 2020). "Our results suggest that high expression of IL-17A is more related to protection than necrosis in a mouse model of pulmonary TB induced by M. bovis strains." (PMID 39024223, 2024). "In conclusion, IL-17A played a protective role in the immune response against high- and low-virulence M. bovis strain infections in our murine model of progressive pulmonary TB." (PMID 39024223, 2024). "We used two M. bovis isolates with different levels of virulence and high IL-17A production to study this important cytokine’s contrasting functions in a BALB/c mouse model of pulmonary TB." (PMID 39024223, 2024). "For example, IL-23 and IL-17A have been shown to play a critical role in the expression of vaccine-induced immunity against pulmonary tuberculosis." (PMID 39772023, 2024). "Compared to healthy people, CD4+ T cells producing IL-22 and IL-17A have been reported to be upregulated in BAL fluids of pulmonary TB patients, indicating their probable contribution to anti-mycobacterial responses." (PMID 30386336, 2018). "This hypothesis could explain why BCG vaccination, which induces strong IFN-γ, but far weaker IL-17A, responses, has demonstrable protection against disseminated Mtb infection in infants and children but less so against primary pulmonary TB." (PMID 36749098, 2023). "We also examined whether neutralizing the IL-6 receptor affected PPD-induced changes in the frequency of IFN-γ-, IL-2-, TNF-α-, and IL-17A-producing cells in pulmonary TB patients with T2DM." (PMID 27783671, 2016). "The aim of our study was to investigate whether IL6–174 G>C SNP and IL17A -197 G>A polymorphism and additional cytokine genes involved in immune response to MTB (IL2, IL4, IL10, IFNG and TNF) are associated with genetic susceptibility to pulmonary TB (PTB)." (PMID 26840977, 2016). "Therefore, the aim of this study was to verify if IFNG, IL12B, TNF, IL17A, IL10, and TGFB1 gene polymorphisms influence the immune response of Brazilian patients with pulmonary tuberculosis (PTB) at different time points of antituberculosis treatment (T1, T2, and T3)." (PMID 23634300, 2013). "The T cells of patients with lymphatic filariasis or pulmonary tuberculosis expressed high levels of IL-24, suppressing Th1 and Th17 cells into producing their signature cytokines, IFN-γ and IL-17A, respectively." (PMID 36233291, 2022). "Additionally, lymphocyte populations present in the lung of pulmonary TB patients are Th1 (CD4+IFN-γ+CXCR3−), Th17 (CD4+IL-17A+CXCR3−), and Th1/Th17 (CD4+IFN-γ+IL-17A+CXCR3−)." (PMID 36009042, 2022). "The frequency of IFN-γ- (1.7-fold, p = 0.0002), IL-2- (2.1-fold, p = 0.0001), TNF-α- (1.6-fold, p = 0.0005), and IL-17A- (2-fold, p = 0.0004) producing cells was significantly higher in diabetic than in non-diabetic pulmonary TB patients." (PMID 27783671, 2016). "The lack of protection against pulmonary tuberculosis further suggests that the generation of IL-17A through vaccination may be a prerequisite for the development of a successful long-lasting memory immune response." (PMID 39772023, 2024).
schizophrenia (42 papers, 2013 to 2025). A major psychotic disorder characterized by abnormalities in the perception or expression of reality. "Finally, with the knowledge that T cell networks have consistently been linked to the pathogenesis of schizophrenia, the functional role of the Th17 pathway in schizophrenia was assessed and involved evaluation of the G197A single nucleotide polymorphism associated with production of IL-17A." (PMID 33746786, 2021). "Polymorphic variants of the IL1B, IL6, IL6R, IL10, IL17A, and TNFA genes have been associated with schizophrenia." (PMID 37510364, 2023). "Among pro-inflammatory cytokines, the levels of interleukin (IL)-1α, IL-6, IL-11, IL-12A, IL-15, IL-17A, and granulocyte colony-stimulating factor (G-CSF) in tears were elevated in the schizophrenia group (all P < 0.01)." (PMID 35223927, 2022). "Among pro-inflammatory cytokines, the levels of interleukin (IL)-1α, IL-6, IL-11, IL-12A, IL-15, IL-17A, and granulocyte colony-stimulating factor (G-CSF) in tears were significantly higher in patients with schizophrenia than that in normal controls (all P < 0.01)." (PMID 35223927, 2022). "Bizarre behavior and apathy could relate to IL-17A driven inflammation in a specific subset of patients with schizophrenia." (PMID 33182582, 2020). "In addition, the IL-17 family is the newest subclass of cytokines, and a recent case-control study suggested that elevated IL-17A level may serve as a potential biomarker for schizophrenia." (PMID 39831058, 2024). "We found a decrease in the IL-17A level during 6 weeks of SGA therapy in schizophrenia patients without MetS." (PMID 34065135, 2021). "Notably, IL17a identified alterations in signaling by ERBB2 factors, which is a pathway of particular relevance to schizophrenia given its interaction with neuregulin-1 to mediate cell adhesion, its potential role in schizophrenia risk, as well as antipsychotic response/treatment." (PMID 34158620, 2021).
coronary artery disease (41 papers, 2012 to 2025). "The genotypes G/A and A/A have been reported to be associated with the increased production of IL-17A in a recent study on coronary disease." (PMID 34290697, 2021). "The role of interleukin 17A (IL-17A) in the inflammatory process has caused interest in the potential significance of IL-17A as a biomarker for coronary artery disease (CAD)." (PMID 25615631, 2015). "IL-17A contributes to the impairment of blood vessel function, and higher levels of IL-17A have been found in patients with acute coronary artery syndromes compared to those with stable coronary artery disease." (PMID 39104857, 2024). "Accepting that SA is a less severe manifestation of the inflammatory process than the symptomatic disease, the higher percentages of gene methylation in SA individuals than in pCAD patients is congruent with the role of IL-17A in coronary artery disease." (PMID 38132456, 2023). "The serum profiling reveals elevated values of IL-17A, IL-6, C-X-C motif chemokine ligand 10 (CXCL10) and higher values of markers associated with coronary artery disease." (PMID 33921718, 2021). "realized in patients with stable and unstable coronary artery disease, IL-17A was significantly increased in patient with MI." (PMID 29166391, 2017). "The expression of IL-17A was increased in patients with coronary artery disease (CAD) and IS." (PMID 29262579, 2017). "Accumulative evidences gathered recently proved that IL-17A, the proinflammatory cytokine, might serve as a proatherogenic agent in coronary heart disease." (PMID 22808218, 2012).
small cell lung carcinoma (41 papers, 2019 to 2025). Small cell lung cancer (SCLC) is a highly aggressive malignant neoplasm, accounting for 10-15% of lung cancer cases, characterized byrapid growth, and early metastasis. "Alternatively, elevated serum IL-17A has been reported in small cell lung cancer patients at mean levels of 24 pg/mL compared to 12 pg/mL in controls and at comparable levels to other studies with mixed-staged NSCLC cohort." (PMID 39329890, 2024).
allergic rhinitis (40 papers, 2011 to 2025). Inflammation of the nasal mucous membranes caused by an IgE-mediated response to external allergens. "In this study, we used an allergic rhinitis mouse model and found that IL-17A deficiency reduced eosinophils important to allergic rhinitis." (PMID 28046055, 2017). "In the allergic rhinitis model, IL-17A deficiency significantly decreased nasal symptoms, serum IgE levels, and eosinophil recruitment to the nasal mucosa." (PMID 28046055, 2017). "Consistent with other studies, our results in an allergic rhinitis mouse model confirmed that IL-17A deficiency is associated with decreased serum IgE production and IL-4 expression in nasal tissue." (PMID 28046055, 2017). "In conclusion, decreased eosinophil infiltration by IL-17A deficiency in allergic rhinitis is attributed at least in part to a decreased chemotactic response of eosinophils via the CCL7/CCR3 pathway." (PMID 28046055, 2017). "IL-17A deficiency suppressed eosinophil infiltration and reduced symptoms by controlling early- and late- phase responses in an animal model of allergic rhinitis." (PMID 28046055, 2017). "Additionally, IL-17A deficiency attenuated allergic inflammation in a mouse model of allergic rhinitis." (PMID 28046055, 2017). "The suppression of nasal inflammation due of IL-17A deficiency in allergic rhinitis is partly responsible for the regulation of CCL7 secretion and eosinophil infiltration, which may be regulated via the CCL7/CCR3 pathway." (PMID 28046055, 2017). "Thus, IL-17A deficiency may play an important role in the development of allergic rhinitis by reducing Th2 cytokine levels." (PMID 28046055, 2017). "SHEDs were shown to reduce IL-17A levels in the spleens of allergic rhinitis mice and downregulate IL-17A secretion from peripheral blood mononuclear cells derived from patients with allergic rhinitis." (PMID 35909660, 2022). "In this study, we assessed the contribution of IL-17A to eosinophil-related inflammation via the CCL7/CCR3 pathway in experimental allergic rhinitis." (PMID 28046055, 2017). "This is consistent with our results obtained from a model of allergic rhinitis: the infiltrating eosinophil number and IL-5 mRNA levels in nasal mucosa were significantly decreased in the IL-17A KO-OVA group compared with the WT-OVA group." (PMID 28046055, 2017). "Results of a 2015 report on an IL-17A-KO ovalbumin-induced allergic rhinitis model were inconsistent with our current findings." (PMID 28046055, 2017). "IL-17A and oxidative stress are involved in the development and progression of allergic rhinitis by the activation of nasal epithelial cells." (PMID 27212811, 2016). "On the other hand, higher levels of IL-17A were observed in the nasal wash from children with allergic rhinitis compared to healthy control, suggesting the relevant action of IL-17A in the nasal inflammation." (PMID 27212811, 2016). "Moreover, systemic IL-26 and IL-17 A concentrations amongst allergen-sensitized children were not clearly different with respect to other allergic manifestations, namely eczema, allergic rhinitis, or a history of one or more food allergies." (PMID 38622712, 2024). "This study was undertaken to determine whether eosinophil migration to the nasal mucosa in response to IL-17A is regulated by the CCL7/CCR3 pathway in a mouse model of allergic rhinitis." (PMID 28046055, 2017). "Consequently these results suggest that IL-17A regulates eosinophil inflammation via the CCL7/CCR3 pathway in a mouse model of allergic rhinitis." (PMID 28046055, 2017). "However, the exact relationship among CCL7, eosinophils, and IL-17A in allergic rhinitis in the upper airway remains unclear." (PMID 28046055, 2017). "IL-17A knockout (KO) and wild-type (WT) BALB/c mice were injected intraperitoneally and challenged intranasally with OVA to induce allergic rhinitis." (PMID 28046055, 2017).
allergic rhinitis (continued). "Thus, in this study, we investigated the regulation of eosinophil inflammation by IL-17A and the involvement of the CCL7/CCR3 pathway in a mouse model of allergic rhinitis." (PMID 28046055, 2017).
Hyperglycemia (40 papers, 2012 to 2026). An increased concentration of glucose in the blood. "have reported that mRNA expression in the pancreas and serum level of IL-17A increase in Akita mice compared with WT mice and diabetic signs, such as hyperglycemia, hypoinsulinemia, and inflammatory response, are alleviated in Akita IL-17A deficient mice." (PMID 38887289, 2024). "In contrast, it has been shown that IL-17A KO on the NOD background have comparable incidence of hyperglycemia to NOD mice with a WT allele for IL-17A." (PMID 22229105, 2012). "A recent study described that miRNA-155 deficiency promotes nephrin acetylation and decreases renal damage in hyperglycemia induced nephropathy, effects that were associated with inhibited IL-17A production through enhancement of suppressor of cytokine signaling 1 (SOCS1) expression." (PMID 31963845, 2020). "In our mechanistic studies, we discovered that hyperglycemia activates transcription factor- RORγt (retinoic acid-related orphan receptor-γt) in circulating Th17 (Thelper-17) cells, which induces IL-17A production." (PMID 36674854, 2023). "Hyperglycemia also reduced IL‐17A expression suggesting further impairment of immune responses during acute hyperglycemia." (PMID 27042306, 2016). "We tested whether the risk of IL-17A for GDM under the recessive model differed among patients with or without a history of GDM, abortion, family history, being overweight, or hyperglycemia." (PMID 40238306, 2025). "Since anti-IL17A monoclonal antibodies inhibit serum glucose levels in both mice and humans, ultimately improving hyperglycemia, we examined whether SRG3 overexpression modulates IL17-producing immune cells in the adipose tissues of B10.PL mice." (PMID 39519233, 2024). "In addition to stimulating IL-17A production, hyperglycemia also enhanced the expression of the IL-17A receptor in Muller glia." (PMID 32429598, 2020). "Hyperglycemia-induced cytokines included T1/Th17 cytokines (IFN-γ, IL-17A, and CCL-20) that echo a T2D profile (black bars, right)." (PMID 38794641, 2024). "We show that short‐term hyperglycemia decreases IL‐6 expression in CD14++CD16+ intermediate monocytes and IL‐17A expression." (PMID 27042306, 2016).
rheumatic diseases (40 papers, 2011 to 2025). "IL-17A and IL-17F produced by Th17 cells have been linked to the development and chronicity of synovial inflammation in rheumatic diseases, including JIA." (PMID 39125893, 2024). "Among currently analysed genetic variants, IL-17A rs2275913 and IL-17F rs763780 have been previously extensively studied for associations with various rheumatic disorders." (PMID 34744511, 2021). "Notably, disruption of the IL-17A signal has been associated with the development and progression of various autoimmune or autoinflammatory diseases, such as rheumatic diseases." (PMID 36350619, 2022). "The results of efficacy and safety from 3 controlled trials of PsA and 2 trials of AS, respectively, enrolling a total number 1045 and 620 patients, led to the approval of SCK, a fully human monoclonal antibody targeting and neutralizing IL-17A, for the treatment of the two rheumatic disorders." (PMID 28659665, 2017). "Additionally, these results may support the further treatment selection strategy targeting IL-17A, TNFα, or other Th17-related cytokines, ultimately improving the management of rheumatic diseases by identifying the biologically rational treatment or combination for the patients." (PMID 38292069, 2024).